PARP14 (poly(ADP-ribose) polymerase family member 14)
Description:
ADP-ribosyltransferase that mediates mono-ADP-ribosylation of glutamate residues on target proteins. In contrast to PARP1 and PARP2, it is not able to mediate poly-ADP-ribosylation. Has been shown to catalyze the mono-ADP-ribosylation of STAT1 at 'Glu-657' and 'Glu-705', thus decreasing STAT1 phosphorylation which negatively regulates pro-inflammatory cytokine production in macrophages in response to IFNG stimulation. However, the role of ADP-ribosylation in the prevention of STAT1 phosphorylation has been called into question and it has been suggested that the inhibition of phosphorylation may be the result of sumoylation of STAT1 'Lys-703'. Mono-ADP-ribosylates STAT6; enhancing STAT6-dependent transcription. In macrophages, positively regulates MRC1 expression in response to IL4 stimulation by promoting STAT6 phosphorylation. Mono-ADP-ribosylates PARP9.
Synonyms: ARTD8; PARP-14; BAL2; KIAA1268; pART8
Tractability: Small molecule: a structure with a bound ligand is known; a high-quality ligand is known; it has a high-quality binding pocket. Antibody: its Gene Ontology location is reachable by antibodies, with high confidence. PROTAC: ubiquitination databases record sites on it; its protein half-life has been measured; a small molecule that binds it is known.
Target class: Enzyme; Transferase
Gene: Protein-coding gene on chromosome 3 (122,680,839 to 122,730,840, forward strand). Ensembl gene ENSG00000173193.
Subcellular location: Nucleus; Cytoplasm
Subcellular location (Human Protein Atlas): Cytosol
Pathways (Reactome):
Disease: Maturation of nucleoprotein
Metabolism: Nicotinate metabolism
Gene Ontology:
Molecular function: enzyme binding; NAD+ poly-ADP-ribosyltransferase activity; NAD+-protein mono-ADP-ribosyltransferase activity; NAD+-protein-glutamate ADP-ribosyltransferase activity; protein binding; transcription corepressor activity; NAD+ binding
Biological process: negative regulation of gene expression; negative regulation of type II interferon-mediated signaling pathway; negative regulation of tyrosine phosphorylation of STAT protein; positive regulation of interleukin-4-mediated signaling pathway; positive regulation of tyrosine phosphorylation of STAT protein; NAD+ catabolic process; negative regulation of DNA-templated transcription; protein poly-ADP-ribosylation
Cellular component: cytoplasm; cytosol; membrane; nucleus
Genetic constraint (gnomAD): Loss-of-function variants: 44 observed, 130.39 expected, observed/expected ratio (o/e) 0.34, 90% interval 0.26 to 0.43. The upper end of that interval is the gene's LOEUF score, 0.43, which puts it in group 1 of 6, group 1 being the genes least tolerant of losing a copy. Missense variants: 1,522 observed, 1,964.3 expected, observed/expected ratio (o/e) 0.77, 90% interval 0.74 to 0.81. Synonymous variants: 646 observed, 734.66 expected, observed/expected ratio (o/e) 0.88, 90% interval 0.82 to 0.94.
Homologues: Orthologues: chimpanzee PARP14 (99% identical), macaque PARP14 (93% identical), pig PARP14 (70% identical), dog PARP14 (68% identical), rabbit PARP14 (68% identical), mouse Parp14 (63% identical), rat Parp14 (63% identical), guinea pig PARP14 (62% identical), tropical clawed frog parp14.2 (38% identical), zebrafish parp14rs1 (33% identical). Paralogues in human: PARP15 (20% identical), PARP9 (13% identical), PARP10 (11% identical), ZC3HAV1 (8% identical), PARP12 (8% identical), TIPARP (7% identical), PARP11 (5% identical), ZC3HAV1L (2% identical).
Diseases named in the same sentence as PARP14 in open-access papers:
PARP14 is named in the same sentence as 70 diseases in open-access papers, as found by Europe PMC text mining. Sharing a sentence is not in itself a finding about the gene and the disease. The quoted sentences say what the papers report.
multiple myeloma (19 papers, 2015 to 2025). "Given the role of STAT6 in B-cell survival, PARP14 is also implicated in promoting B-cell specific tumorigenesis such as diffuse large B-cell lymphoma and multiple myeloma." (PMID 36814782, 2023). "PARP14 has been shown to be critical for human multiple myeloma cell survival, and PARP14 levels are strongly linked with cancer progression and poor prognosis." (PMID 35652091, 2022). "These authors also found that PARP14 is highly expressed in myeloma plasma cells and associated with poor survival." (PMID 34976832, 2021). "In multiple myeloma, where PARP14 is upregulated and implicated in mitophagy induction, PARP14 inhibition could provide clinical advantages." (PMID 40741921, 2025). "This study demonstrated a role for PARP14 in promoting survival of multiple myeloma cells via Jun N-terminal kinase (JNK) signaling." (PMID 36814782, 2023). "The results of this study indicate that PARP14 promotes JNK2 dependent survival of multiple myeloma cells by inhibiting JNK1." (PMID 36814782, 2023). "Concerning its involvement in cancer disease (recently reviewed), it was found that PARP14 is overexpressed in multiple solid and liquid tumors such as large B cell lymphoma, multiple myeloma, prostate cancer and hepatocellular carcinoma." (PMID 37570820, 2023). "Recent research has identified the molecular processes of PARP14 as a new prospective therapeutic target for a variety of malignancies, such as prostate cancer, multiple myeloma, ovarian cancer, diffuse large B-cell lymphoma, and breast cancer." (PMID 36567857, 2022). "PARP14 was shown to be a newly produced drug target for carcinomas (such as diffuse large B-cell lymphoma, multiple myeloma, prostate carcinoma, and hepatocellular carcinoma) and allergic inflammation." (PMID 33679872, 2020). "Subsequently, current literatures are presented to reveal the molecular mechanisms of PARP14 as a novel drug target for cancers (e.g., diffuse large B-cell lymphoma, multiple myeloma, prostate cancer, and hepatocellular carcinoma) and allergic inflammatory." (PMID 30890936, 2019). "PARP14 is involved in normal immune function through the IL-4 signaling pathway and is a prosurvival factor in multiple myeloma and hepatocellular carcinoma." (PMID 30941331, 2019). "Of note, PARP14 is a key regulator of B-cell survival and is highly expressed in multiple myeloma plasma cells." (PMID 26192630, 2015). "PARP14 induces Drp1 expression to increase mitophagy and drug resistance in multiple myeloma." (PMID 40615369, 2025). "PARP14, overexpressed in multiple myeloma, functions as a transcriptional co-activator for STAT6, facilitating the Th2 immune response, promoting metabolic changes to an anaerobic state, and activating cell survival pathways through JNK2 and the PGI/AMF complex." (PMID 39057711, 2024). "Lomitapide’s effects may also extend to hematological malignancies, with recent evidence indicating that targeting PARP14 with lomitapide attenuates drug resistance via DRP1-induced mitophagy activation in multiple myeloma." (PMID 39057711, 2024). "Additionally, inhibiting PARP14 using the specific inhibitor PJ-34 sensitized multiple myeloma cells to therapeutic agents such as dexamethasone and bortezomib." (PMID 36814782, 2023). "A further study reports that PARP-14 is involved in the survival pathway in multiple myeloma (MM)." (PMID 31130919, 2019). "Intriguingly, JNK2 may regulate PARP14 expression in an indirect manner at the transcriptional or post-transcriptional level, which is beneficial to the survival of myeloma cells." (PMID 30890936, 2019). "In addition, we have recently shown that PARP14 is essential for survival of human multiple myeloma cells and that PARP14 levels positively correlate with disease progression and poor prognosis." (PMID 26258887, 2015). "Inhibition of PARP14 sensitizes cells to anti-myeloma treatments, and thus PARP14 may represent a novel treatment target for other diseases such as SLE." (PMID 26192630, 2015).
multiple myeloma (continued). "Moreover, inhibition of PARP14 enhances the sensitization of MM cells to anti-myeloma agents." (PMID 34976832, 2021). "Therefore, since PARP-14 is involved in a transduction pathway mediated by JNKs, promoting survival in multiple myeloma, we hypothesized the activation of this signaling pathway also in our αTC1.6 cell line, in an inflammatory experimental model." (PMID 31130919, 2019). "In multiple myeloma (MM), Barbareulo showed that c-Jun N-terminal kinase 2 (JNK2) constitutively suppresses JNK1-mediated apoptosis by affecting expression of PARP14." (PMID 34976832, 2021). "Very interesting data in this paper showed that PARP-14 overexpression totally prevented myeloma cells from undergoing apoptosis, induced by JNK2 knockdown: this suggests that PARP-14 is essential in JNK2 dependent survival signaling." (PMID 31130919, 2019). "In addition, PARP14 overexpression, mediated by JNK2, negatively regulates JNK1-dependent apoptosis in the 80% of multiple myeloma." (PMID 37570820, 2023).
hepatocellular carcinoma (14 papers, 2015 to 2025). A malignant tumor that arises from hepatocytes. "The elevated expression level of PARP14 is linked to the unfavourable prognosis of primary hepatocellular carcinoma." (PMID 36567857, 2022). "PARP14 has been associated with the development of inflammatory diseases such as allergic asthma and inflammatory arterial diseases and various types of cancer including B cell lymphoma, prostate cancer, and hepatocellular carcinoma." (PMID 37703374, 2023). "PARP14, a member of the glycosyltransferase family, has been shown to be closely associated with the development of a number of tumors, particularly in pancreatic cancer, hepatocellular carcinoma, and hematologic malignancy." (PMID 37650946, 2023). "Beyond PARP1, PARP14 directly promotes aerobic glycolysis (the Warburg effect) in hepatocellular carcinoma by modulating PKM2, linking ADP-ribosylation to pro-tumor glycolytic bias." (PMID 41460301, 2025). "PARP7 ADP-ribosylates FRA1 to suppress IRF1/IRF3-dependent apoptosis and, finally, PARP14 inhibits the pro-apoptotic gene JNK1 to support metabolic growth in hepatocellular carcinoma." (PMID 41460301, 2025). "Oppositely, in hepatocellular carcinoma cells with a poly(adp-ribose) polymerase family member 14 (PARP14) knockdown, knockdown of PKM2 increased lactate production." (PMID 33796550, 2021). "Establishing the role of PARP14 as a pro-survival factor regulating the Warburg effect, we demonstrate that knockdown of PARP14 impaired the aerobic glycolytic phenotype and survival of both cultured and xenografted hepatoma cells." (PMID 26258887, 2015). "Particularly, PARP14 can promote glycolysis in different tumor models, such as human hepatocellular carcinoma (HCC), by maintaining reduced PKM2 activity; on the other hand, a close relationship between c-myc and AKT has been reported in B lymphomas and AML through the NF-κB/HIF-1α axis." (PMID 37520325, 2023). "Moreover, another study found that PARP14 promoted cancer cell proliferation in hepatocellular carcinoma by promoting the Warburg effect." (PMID 35096828, 2021). "In light of these studies, it has been suggested that PARP14 may be a novel drug target for several cancer types including diffuse large B-cell lymphoma, multiple myeloma prostate cancer and hepatocellular carcinoma." (PMID 35096828, 2021). "In addition, targeting PARP14 enhances the sensitivity of hepatoma cells to antihepatoma drugs." (PMID 36567857, 2022). "In hepatocellular carcinoma (HCC) cells, PARP14 plays a role in promoting cell survival." (PMID 37650946, 2023).
viral infections (14 papers, 2018 to 2025). "Experiments on murine and human cells also indicate the role of PARP14 in the induction of type I interferon production in response to bacterial and viral infections." (PMID 39452702, 2024). "More studies are needed to identify specific roles for PARP14 during viral infections, determine its targets following infection, and elucidate the mechanisms by which PARP14 modulates inflammatory pathways." (PMID 35679255, 2022). "First, PARP14 expression is stimulated in a variety of viral infections such as Chikungunya virus and β-coronaviruses like MHV and severe acute respiratory syndrome coronavirus 2 (SARS-CoV-2)." (PMID 35679255, 2022). "On the other hand, PARP9 is an important molecule that provides protection against lethal viral infections through interferon responses, and as PARP14, also participates in the polarization of macrophages towards the M2 phenotype." (PMID 33913542, 2021). "PARP14 has an emerging role in viral infections, and this article considers its potential mechanisms for action in either a pro- or anti-viral manner." (PMID 33467912, 2021). "While no in-vivo PARP14 substrates are yet known, PARP14 has been reported to play an important role in the immune response against viral infections, including those caused by coronaviruses." (PMID 37326024, 2023). "However, PARP14 expression is also induced by interferon (IFN), and it enhances host IFN responses to lipopolysaccharide (LPS), poly(I:C), and viral infection, indicating a role for PARP14 in restricting viral and bacterial infections." (PMID 35679255, 2022). "Several pieces of circumstantial evidence indicate that PARP14 may be involved in the repression of viral infections." (PMID 35679255, 2022). "Since PARP14 is implicated in several diseases, including cancer, a full exploration of its potential role in countering virus infection is needed to establish a platform to determine its targets, elucidate the mechanisms by which PARP14 modulates inflammatory pathways, and develop novel therapies." (PMID 35679255, 2022). "The poly [ADP-ribose] polymerase transcription factor PARP14, which was described to be important for T cell differentiation into Th2, Th17 and Tfh cells, was shown by Western blotting (WB) to be more abundant after virus infection." (PMID 29980615, 2018). "The results revealed that, upon viral infection, the mRNA levels of NAD+-consuming enzymes, including Sirt1-7, Parp1, Parp10, Parp12, Parp14, and CD38, were substantially upregulated." (PMID 40006932, 2025). "PARP12 and PARP14, as interferon-induced genes (ISG), were found to block RNA translation of viruses and played a potential role in cellular defenses against viral infections." (PMID 38543614, 2024). "PARP14 also induces IFN-I following poly(I:C) treatment, a double-stranded RNA mimic, and virus infection." (PMID 35679255, 2022). "This is of particular importance given that PARP14 has been reported to have a crucial role in responding to coronavirus infection and mediating inflammation, while PARP9/DTX3L has been indicated in controlling viral infection and protecting against Mycobacterium tuberculosis." (PMID 38834853, 2024).
prostate carcinoma (9 papers, 2016 to 2024). A carcinoma that arises from epithelial cells of the prostate gland. "Mechanistically, DTX3L forms a complex with PARP9 and PARP14 and mediates the proliferation as well as drug resistance of prostate cancer cells." (PMID 34976832, 2021). "Gemcitabine-resistant prostate carcinoma depends on constitutively active NF-κB signaling and expresses high levels of PARP14 (ARTD8), which in turn correlates with poor patient survival." (PMID 34725336, 2021). "Downregulation of PARP14 by siRNA decreases NF-κB activation in gemcitabine-resistant prostate carcinoma cells and consequently promotes apoptosis, suggesting that PARP14 is important for cell viability and required for constitutive NF-κB signaling." (PMID 34725336, 2021). "Of note, genetic inhibition of PARP9 and PARP14 was shown to increase chemotherapy efficacy in prostate cancer cells." (PMID 27791205, 2016). "Moreover, it was demonstrated for the first time that the enzymatic activity of PARP14 is necessary for the survival of prostate cancer cells." (PMID 34976832, 2021).
lymphoma (7 papers, 2019 to 2023). A malignant (clonal) proliferation of B- lymphocytes or T- lymphocytes which involves the lymph nodes, bone marrow and/or extranodal sites. "Furthermore, PARP14 accelerates lymphoma growth and, conversely, PARP14 deficiency prohibits c-Myc-induced B-lymphoid oncogenesis in a mice model." (PMID 30890936, 2019). "DTX3L is reported to regulate the ubiquitin modification of PARP family proteins (PARP1, PARP2, PARP9, PARP14), promoting proliferation, migration and chemotherapy resistance of lymphoma, glioma, and melanoma." (PMID 38304253, 2023). "Our data support a model in which increased PARP14 levels drive a self-reinforcing microcircuit that promotes the assembly of the STAT6 enhanceosome complex in IL-4 stimulated STAT6MUT lymphoma cells, thereby further amplifying STAT6-dependent gene activation." (PMID 35851155, 2022). "Here we describe a therapeutically targetable PARP14-mediated self-reinforcing regulatory circuit that amplifies IL-4 induced STAT6-dependent gene expression in STAT6MUT lymphoma cells." (PMID 35851155, 2022). "The results showed that PARP14 (mediated by IL-4) is a key component of the pro-survival signaling pathway for lymphoma." (PMID 30890936, 2019). "PARP14 was first described as B-cell aggressive lymphoma protein-2 (BAL2), along with PARP9/BAL1 and PARP15/BAL3, as frequently overexpressed in fatal high-risk lymphoma." (PMID 37507011, 2023). "RNA sequencing identified PARP14 -a transcriptional switch and co-activator of STAT6- among the top differentially upregulated genes in IL-4 stimulated STAT6MUT lymphoma cells and in STAT6MUT primary FL cells." (PMID 35851155, 2022). "PARP-14 (poly-ADP Ribose Polymerase-14), a member of the PARP family, belongs to the group of Bal proteins (B Aggressive Lymphoma)." (PMID 31130919, 2019). "We could indeed confirm direct interaction of PARP14 and STAT6 in IL-4 stimulated lymphoma cells by IP of 3xFlag-tagged STAT6 and immunoblotting for PARP14." (PMID 35851155, 2022). "As such, PARP14 has been implicated in mediating IL-4 induced attenuation of caspase-3 activation, i.e., increased PARP14 levels could contribute to protection against apoptosis and provide a survival advantage to STAT6MUT lymphoma cells." (PMID 35851155, 2022).
pancreatic cancer (6 papers, 2020 to 2025). "PARP14 high expression in human primary pancreatic cancer (PCa) is associated with poor prognosis, and PARP14 promotes the proliferation and gemcitabine chemoresistance of pancreatic cancer cells through activation of NF-κ pathway." (PMID 37650946, 2023). "PARP14 can promote pancreatic cancer (PC) cell proliferation, anti-apoptosis, and GEM resistance, highlighting its potential role as a therapeutic target for PC." (PMID 33679872, 2020). "Furthermore, PARP14 promoted pancreatic cancer cell proliferation, anti‐apoptosis, and GEM (gemcitabine) resistance via its relationship with the NF‐κB signaling pathway, which agrees our research that it has high potential to be an effective drug‐based target." (PMID 32902917, 2020). "For example, PARP10 and PARP14 are highly upregulated by the type I interferon, IFN-β, in pancreatic cancers." (PMID 40000907, 2025). "In order to identify genes which are essential for cellular viability in the absence of PARP14, we performed a genome-wide synthetic lethality CRISPR knockout screen in 8988T pancreatic cancer cells." (PMID 32542389, 2020).
coronary artery disease (5 papers, 2016 to 2025). "Consistent with in vitro studies, PARP14 deficiency indeed mitigated lesion development and inflammatory burden in models of coronary artery disease in mice." (PMID 32029454, 2020). "Due to the well-recognized knowledge that targets identified in basic science often fail in the clinical stage, we performed network analysis that closely linked the network of PARP9, PARP14, and their first neighbor interactors with the human coronary artery disease gene module." (PMID 32029454, 2020). "PARP14 together with PARP9 are also associated with inflammation and human coronary artery disease." (PMID 39823074, 2025).